EGFR (epidermal growth factor receptor)
Diseases named in the same sentence as EGFR in open-access papers (continued):
Sharing a sentence is not in itself a finding about the gene and the disease.
colorectal cancer (continued). "It is well-known that KRAS mutations in patients with colorectal cancer, are associated with no response to anti-EGFR therapies and with consequent significantly lower OS and disease-free survival, due to higher risk of tumor relapse, especially in the lungs." (PMID 33946899, 2021). "To extend our findings linking Tspan6 and EGFR-dependent signaling in colorectal cancer, we investigated whether the expression of Tspan6 can predict a response to the EGFR-targeting therapies in vivo." (PMID 34521767, 2021). "Moreover, cmFOLFOXIRI in combination with anti-EGFR monoclonal antibody (cetuximab) is recommended as the first-choice conversion therapy for left-sided colorectal cancer patients with wild-type RAS/BRAF." (PMID 34567559, 2021). "Based on these findings, we can think that IL13Rα2-specific mAbs might be used in combination with or alternatively to those mAbs currently used for EGFR targeting in colorectal cancer." (PMID 33917458, 2021). "Finally, our findings reveal that PRMT5 promotes EMT through activation of the EGFR/Akt/GSK3β signaling pathway in colorectal cancer cells." (PMID 33495409, 2021). "Furthermore, both c-MET and EGFR expressions show significant correlation with copy number alterations in colorectal cancer." (PMID 34512327, 2021). "Numerous studies have reported that EGFR is a modest to strong prognostic indicator of recurrence-free and overall survival across multiple cancer types, such as breast, head and neck, ovarian, and colorectal cancers." (PMID 33995681, 2021). "On the other hand, epidermal growth factor receptor (EGFR)-inhibitor, targeting the EGFR on the surface of cell is used in cases of colorectal cancer without mutations in the RAS-genes." (PMID 33916923, 2021). "Similarly, EGFR is overexpressed in 60–80% of colorectal cancers and specific antibody therapies, including cetuximab and panitumumab, have been used against EGFR and to target its downstream RAS/RAF/MEK/ERK signaling pathway." (PMID 33801965, 2021). "Similarly, other studies reported that EGFR expression was lost in 33% of metastasising primary colorectal cancer tumours." (PMID 33562755, 2021). "Therefore, it is worth exploring the feasibility of dual-targeted VEGF and EGFR in colorectal cancer." (PMID 34663410, 2021). "KRAS mutation is a predictive biomarker commonly used in colorectal cancer to identify patients who will not benefit from treatment with drugs against epidermal growth factor receptor (EGFR)." (PMID 32885400, 2021). "Notably, the recommendations of the National Comprehensive Cancer Network (NCCN) in 2017 were revised as anti‐EGFR therapy restricted to wild‐RAS left colorectal cancer only." (PMID 33939281, 2021). "Cetuximab was approved to treat colorectal cancer prior to its approval for head and neck cancer, and EGFR amplification revealed by IHC was originally considered an indication for the use of cetuximab or other EGFR-targeted antibodies." (PMID 35006440, 2021). "The HT-29 colorectal cancer cell line, which has previously been shown to be resistant to EGFR signalling blockade by cetuximab, due to a downstream mutation in BRAF25, was used to avoid therapeutic effect of cetuximab by EGFR blockade." (PMID 33686177, 2021). "This study was conducted to investigate the effects of AREG on cetuximab response in patients with metastatic colorectal cancer and determine the mode of action via the EGFR signaling pathway using in vitro experiments with both cetuximab-naïve and resistant colorectal cancer cell lines." (PMID 34893673, 2021). "The discovery of the epidermal growth factor receptor (EGFR) and Kirsten Rat Sarcoma virus (KRAS) mutations in cf-DNA, for example, has fuelled interest in lung and colorectal cancer management techniques, which have been shown to be useful for tracking treatment response and prediction of relapse." (PMID 33917435, 2021).
colorectal cancer (continued). "Indeed, the combination of the KRAS-G12C inhibitor MRTX1257 and the EGFR antibody cetuximab is being explored in a phase III trial in patients with advanced colorectal cancer (NCT04793958)." (PMID 34200676, 2021). "In contrast, in the present study, AREG-induced cetuximab resistance may be attributed to direct EGFR activation in RAS/BRAF wild-type colorectal cancer." (PMID 34893673, 2021). "However, aberrant EGFR signaling can lead to cancer and other diseases and EGFR inhibition has been used as treatment for breast, lung, and colorectal cancer." (PMID 34359893, 2021). "Based on existing studies, NOB1 was found to be associated with the 26S proteasome to inhibit apoptosis and ING5 may related to EGFR/PI3K/Akt pathway in colorectal cancer to induce apoptosis." (PMID 33996574, 2021). "Currently, VEGF and EGFR are the most important therapeutic targets of colorectal cancer." (PMID 33634965, 2021). "Overall, these results demonstrated that the concentration-dependent anoikis-inducing effects of SAE in HCT116 colorectal cancer cells proceeds by inducing the intrinsic apoptotic pathway through the regulation of anoikis-related signaling proteins such as EGFR, caveolin-1, Src, and Akt." (PMID 34094906, 2021). "RAS-mutated colorectal cancer will not benefit from EGFR-directed treatment with cetuximab or panitumumab." (PMID 35582302, 2021). "However, no work had been conducted to assess the impact of Anthos or anthocyanins on Src in any cancer model or Anthos on EGFR in a colorectal cancer model." (PMID 34926717, 2021). "It is possible that claudin upregulation could come from two signaling pathways: EGFR and Wnt; both are able to increase claudin expression and are permanently activated in many cancer types, including colorectal cancer." (PMID 34638619, 2021). "Moreover, RAC1B inhibition sensitises cetuximab resistant human tumour organoids to the effects of EGFR inhibition, outlining a potential therapeutic target for improving the clinical efficacy of EGFR inhibitors in colorectal cancer." (PMID 33879799, 2021). "However, with time, colorectal cancer patients experience resistance to EGFR inhibitors due to ability of RAS to activate the same downstream signaling pathway as EGFR that results through acquired resistance." (PMID 33801965, 2021). "Mutated KRAS is reported in approximately 35%-45% of colorectal cancers and >90% of pancreatic ductal adenocarcinoma (PDAC) correlating with abnormal metabolic rates, enhanced glucose uptake and resistance to EGFR-targeted therapies as well as preoperative chemoradiotherapy (CRT) 8-10." (PMID 33664850, 2021). "The study found that the potential targets of calycosin on colorectal cancer were ERα, ERβ, ATP-binding cassette subfamily G member 2, breast cancer type 1 susceptibility protein, CYP19A1, and epidermal growth factor receptor (EGFR)." (PMID 34035829, 2021). "EGFR is highly expressed in primary cell cultures of human colorectal carcinomas." (PMID 34766923, 2021). "Peiminine induces apoptosis through both extrinsic and intrinsic apoptotic pathways in liver cancer, represses proliferation and growth of colorectal carcinoma by inducing autophagic cell death, and serves as an adriamycin chemosensitizer via the EGFR/FAK pathway in gastric cancer." (PMID 34867399, 2021). "We hypothesized that a nutritional intervention designed to reduce aerobic glycolysis may boost the EGFR-directed antibody (Ab)-based therapy of pre-existing colitis-driven colorectal carcinoma (CRC)." (PMID 34830971, 2021). "In experimental murine colitis models, blockade of EGFR by the tyrosine kinase inhibitor gefitinib or knockout of the EGFR resulted in exacerbated colitis and colitis-driven colorectal carcinoma, indicating a crucial role of EGFR signaling cascades in intestinal tissue homeostasis." (PMID 34830971, 2021). "In colorectal cancer, the receptor for epidermal growth factor (EGFR) is highly expressed." (PMID 32168791, 2020).
colorectal cancer (continued). "There is data indicating that EGFR protein expression in colorectal cancer is a negative prognostic factor associated with advanced-stage and lymphovascular invasion." (PMID 32155907, 2020). "The selection of colorectal cancer patients for anti-epidermal growth factor receptor (EGFR) antibody therapy is based on the determination of their RAS mutation status—a strongly negative predictive factor—since the protein target, EGFR, is not a reliable predictor of therapeutic response." (PMID 32155907, 2020). "Our data suggest that CAF composition is important for cetuximab response, specifically highlighting EGF secretion by cetuximab treated CAFs as a previously unknown mechanism of resistance to anti-EGFR treatment in colorectal cancer." (PMID 32481658, 2020). "Cell growth and colony formation assay showed that the inhibition of IRE1α activity could suppress EGFR driven colorectal cancer cell proliferation." (PMID 32489465, 2020). "Furthermore, it was also recently discovered that left-sided colorectal cancers respond significantly better to anti-EGFR therapies than do right-sided colorectal cancers." (PMID 32155907, 2020). "Inhibition of EGFR is usually combined with other chemotherapy in colorectal cancer treatment." (PMID 32489465, 2020). "Further, it has been known since recently that m-CRC with mutated RAS is resistant to anti-EGFR therapies, and those with MSI phenotype are sensitive to immunotherapy, but colorectal cancer with BRAF mutation/s is awaiting such a specific chemotherapeutic approach." (PMID 33738242, 2020). "In this work, we investigated one of these possible mechanisms, showing that E2F2 could have a role not only in being a direct effector of miR-31 in the regulation of the colorectal cancer proliferation, but also in the resistance to treatment with anti-EGFR." (PMID 32164324, 2020). "Our results showed that IRE1α RNase activity is aberrantly elevated in colorectal cancer, and EGFR signaling could activate IRE1α/XBP1s possibly through EGFR-MEK-ERK pathway." (PMID 32489465, 2020). "For example, lung and colorectal cancers with mutations in KRAS or BRAF do not respond to treatment with anti-EGFR therapies." (PMID 32087721, 2020). "In colorectal cancer (CRC), activating mutations in KRAS (codons 12, 13, 61, 117 and 146), NRAS (codons 12, 13, 61, 117 and 146), and BRAF (V600E) confer resistance to anti-epidermal growth factor receptor (EGFR) therapy including Cetuximab and Panitumumab1–4." (PMID 31953485, 2020). "It has not yet been determined whether FAK is involved in the regulation of EMT in colorectal cancer cells through the EGF/EGFR signaling pathway." (PMID 32148496, 2020). "Relevant for our working hypothesis, mutations in RAS itself or its effectors are known mechanisms of acquired resistance to anti-EGFR antibody therapies in colorectal cancers." (PMID 32183295, 2020). "The EGFR signaling pathway plays an important role in the development of colorectal cancer." (PMID 33680376, 2020). "As it is known that EGFR plays a pivotal role in metabolism of lung and colorectal cancer, we investigated how cetuximab could affect metabolism in CRC cells and if any differential pathway could be activated in combination with VitC." (PMID 32183295, 2020). "The specific mechanism of this process involves the binding of EGF to EGFR, causing FAK phosphorylation, upregulation of miR-217 expression, and downregulation of E-cadherin; this induces EMT and enhances the migrating ability of colorectal cancer cells." (PMID 32148496, 2020). "MS4A12 may promote the proliferation and invasion of colorectal cancer cells by influencing epidermal growth factor receptor." (PMID 32797167, 2020). "Also, the expression of XBP1 was correlated with EGFR in colorectal cancer patients database GSE 38822." (PMID 32489465, 2020). "Meanwhile, the predictive role of EGFR protein expression in RAS wild-type colorectal cancer is still unknown." (PMID 32155907, 2020).
colorectal cancer (continued). "In colorectal cancer, the commonly used therapy is anti-epithelial growth factor receptor (EGFR)." (PMID 33213472, 2020). "In lab experiments, the monoclonal antibody cetuximab was shown to bind EGFR with high affinity, which suggested that cetuximab might have a disposition to slow down the progress of colorectal cancer (by blocking EGFR)." (PMID 32168791, 2020). "Therefore, our results indicated that IRE1α-XBP1s pathway was activated in colorectal cancer and correlated with EGFR expression." (PMID 32489465, 2020). "Similarly, to adrenergic and noradrenergic signaling, muscarinic cholinergic signaling has pro-tumorigenic effects in colorectal cancer by transactivating EGFR." (PMID 33142779, 2020). "In colorectal cancer (CRC), KRAS mutational status is critical for targeted therapy because it can predict the therapeutic response to anti-epidermal growth factor receptor (EGFR) treatment; consequently, KRAS genotyping is routine in patients with metastatic CRC." (PMID 33585224, 2020). "One of the best examples of a negative predictive biomarker is the use of RAS mutations to predict for lack of benefit of anti-EGFR therapy in colorectal cancer." (PMID 32500029, 2020). "If we exclude the select few patients that have microsatellite unstable tumours and that might benefit from immunotherapy, targeted agents commonly used in colorectal cancer treatment fall within 2 main categories: the anti-EGFR or anti-VEGF pathway." (PMID 32977434, 2020). "Detection of ctDNA has demonstrated its relevance in lung or colorectal cancer with the detection of EGFR and KRAS mutations for non-invasive tumors genotyping, treatment response follow-up, and relapse prediction." (PMID 33042820, 2020). "Moreover, mutations in codon 61 in KRAS and NRAS were detected more frequently in colorectal cancer patients with acquired resistance to anti-EGFR therapy than before initiation of anti-EGFR therapy." (PMID 32369927, 2020). "Likewise, in human SW480 cells of colorectal carcinoma, the sialylation of EGFR decreases EGF-mediated cell proliferation." (PMID 33238647, 2020). "Colorectal cancer patients with tumors harboring KRAS mutation are excluded from receiving the otherwise beneficial therapy of anti-EGFR monoclonal antibodies, and currently have no alternate FDA-approved treatment options available." (PMID 31766149, 2019). "Interestingly, ErbB2 activation is present in about 5% of colorectal cancers developing resistance to EGFR-targeted therapies thus supporting investigation of anti-ErbB2 antibodies and related ADCs in these patients." (PMID 32039017, 2019). "It was also reported that activation of the EGFR/Akt pathway by inhibition of hepatocellular carcinoma-related protein-1 suppressed Bim expression in human colorectal cancer cells and contributed to metastasis and poor prognosis in colorectal cancer patients." (PMID 31769426, 2019). "In addition, we identified Macrophage Migration Inhibitory Factor (MIF) as a molecular determinant of the anti-EGFR cetuximab resistance in human colorectal cancer cells." (PMID 31557914, 2019). "We hypothesized that PrPC expression levels may regulate EGFR signaling and that detailed understanding of this signaling pathway may enable identification of resistance mechanisms and new actionable targets in colorectal cancer." (PMID 30478887, 2019). "The findings could potentially lead to early adoption of a clinical algorithm to treat gallbladder cancer patients under neo‐adjuvant or adjuvant settings similar to the one commonly used for anti‐EGFR treatment in colorectal cancer." (PMID 30304546, 2019). "This might also explain the different pattern of response to biological agents, with left-sided colorectal cancer (LCC) more prone to respond to anti-EGFR therapies and right-sided colorectal cancer (RCC) more responsive to antiangiogenic drugs." (PMID 31344798, 2019).
colorectal cancer (continued). "Epidermal growth-factor receptor (EGFR) antibody and EGFR inhibitors (e.g., cetuximab or panitumumab) have been used for developing a promising strategy for the colorectal cancer therapy in EGFR-expressing tumors (i.e., NCT01283334, NCT00522665, NCT01719380, NCT01252628, NCT01256385)." (PMID 30975222, 2019). "Overall, 8.5% of patients harbored an EGFR amplification in their blood-derived cfDNA, with EGFR amplifications being most common in colorectal cancer (16.3% of patients), NSCLC (9.0%), genitourinary cancers (8.1%), cutaneous tumors (7.4%), and breast malignancies (7.3%)." (PMID 31058253, 2019). "Diminished response to treatment with anti-EGFR monoclonal antibodies is found in KRAS-mutant or BRAF-mutant colorectal cancer but these mutations do not impair response to oxaliplatin- (OxPt) or cisplatin-based chemotherapy." (PMID 30792807, 2019). "Enhanced EGFR signaling in colorectal cancer promotes proliferation and cancer progression." (PMID 30478887, 2019). "We have shown how transcriptional adaptation is ultimately responsible for PI3K activation upon vertical suppression of the EGFR/MAPK pathway through the upregulation and cooperative activation of different RTKs in a preclinical model of KRAS-mutated colorectal cancer." (PMID 30691487, 2019). "For example, the use of cetuximab, an anti-EGFR antibody, for treatment of colorectal cancers is limited to patients who do not harbor genetic mutations in the RAS genes." (PMID 31426517, 2019). "However, similar to the findings of the current study, patients with advanced colorectal cancer with high plasma sHRG levels exhibited shorter PFS following anti-EGFR antibody therapy than those with low sHRG31." (PMID 31862929, 2019). "However, the molecular mechanism by which asporin activates the EGFR signaling pathway in gastric and colorectal cancer remains to be investigated both in vitro and in vivo." (PMID 31608236, 2019). "In addition, patients with KRAS-wild type colorectal cancer are treated with the epidermal growth factor receptor (EGFR) antibody cetuximab or panituzumab in combination with chemotherapy." (PMID 31769426, 2019). "We speculate that PrPC can influence cisplatin resistance in colorectal cancer via EGFR signaling to p38 MAPK and regulation of expression of FOXO3a." (PMID 30478887, 2019). "Our finding that the survival signaling pathways of Fas could be promptly activated by EGF, the cognate ligand of the EGFR, signifies a close connection between the two pathways in colorectal cancer cells." (PMID 30127519, 2018). "Interestingly, three gastrointestinal cancer types including pancreatic, gastric, and colorectal cancer, and bladder cancer were then identified as the most promising cancer types for cross-cancer prediction from EGFR-mutant NSCLC by our CONCORD analysis." (PMID 29416679, 2018). "Interestingly, in colorectal cancer, the EGFR antibody, cetuximab, showed benefit in clinical trials, but the benefits did not hold for patients with Ras mutations." (PMID 29910823, 2018). "The growth of colorectal cancer cells is dependent on or facilitated by EGFR, hence, we explored whether EGFR and related signaling may be involved in OGN-induced cell inhibition." (PMID 29499765, 2018). "EGFR inhibitors prevent the growth of colorectal cancer cells and have shown benefit in the treatment of metastatic colorectal cancer patients, whether used as single agents or in combination with chemotherapy." (PMID 29652830, 2018). "Therefore, the aim of this study was to identify the relevant driver genes that maintain cancer stemness in epidermal growth factor receptor (EGFR)-positive colorectal cancer (CRC) cells and to discover effective therapeutic agents against these genes." (PMID 30068339, 2018). "In colorectal cancer (CRC), RAS gene mutations may serve as a mechanism of secondary resistance to EGFR inhibitors (EGFR-ab), and cftDNA testing has been shown to be a sensitive method for detecting CRC clonal evolution." (PMID 30430428, 2018).